AREG (amphiregulin)
Diseases named in the same sentence as AREG in open-access papers (continued):
Sharing a sentence is not in itself a finding about the gene and the disease.
tumor (continued). "When proteolytically processed by the cell membrane proteases TACE/ADAM17, AREG is secreted, behaves as an autocrine or paracrine factor, and may thus also modify the tumor microenvironment." (PMID 38727313, 2024). "We found higher levels of AREG mRNA expression in tumor tissue than in adjacent normal tissue." (PMID 38904011, 2024). "EREG and AREG are attractive therapeutic targets for CRC based on their high expression across tumors with different mutational statuses, lower expression in normal tissues, and potential roles in tumor progression." (PMID 40727266, 2024). "Interestingly, addition of EGF instead of AREG would have reduced intra-tumor heterogeneity and generated worse JSD scores." (PMID 37776423, 2024). "The violin plot showed the cell-cell interactions while giving the different ligands and receptors in the EGF signaling pathway, and the results showed that C1 SRSF7+ MCs subtype and tumor-cells were mainly contacted with AREG as a ligand and EGFR or ERBB2 as receptors." (PMID 39430754, 2024). "Functional assays indicated that silencing of AREG impeded PC cell proliferation, invasion, and migration, but the reasons for its high expression and the molecular mechanism that facilitates tumor progression remain unclear." (PMID 37604948, 2023). "AREG mAb treatment significantly inhibited tumor growth and prolonged overall survival." (PMID 37611111, 2023). "AREG, one of the seven ligands that bind and activate EGFR, can promote the differentiation of T cells into Tregs in the tumor microenvironment, and targeting AREG in the tumor microenvironment may inhibit tumor invasion and immunosuppression." (PMID 37538176, 2023). "Among them, the top up-regulated genes in tumor cells were those related to cancer progression (eg, AREG, CCL3, PLEKHA5, VCAM1 and MCM7), which might be the targets of innovative treatments." (PMID 36417130, 2023). "Furthermore, we also detected high expression of S100A8, PDGF and VEGF in tumor cells after eliminating AREG and bFGF once triggered." (PMID 36639835, 2023). "Additionally, targeting AREG and bFGF will be effective in inhibiting tumour growth and preventing tumour recurrence." (PMID 36639835, 2023). "The data from the present study suggest that AREG and bFGF levels in patient tissue and serum might be explored as useful biomarkers predicting tumour cell repopulation and recurrence." (PMID 36639835, 2023). "Consistently, we demonstrated that chemoradiotherapy could increase AREG protein levels in the conditioned culture medium of dying tumour cells." (PMID 36639835, 2023). "Additionally, the overexpression of AREG and EPCAM is associated with tumor progression and unfavorable survival outcomes in multiple cancer types." (PMID 36341526, 2023). "Moreover, the expression of the EGFR ligands heparin-binding EGF (Hbegf), amphiregulin (Areg) and epiregulin (Ereg) was also markedly elevated in tumor tissues." (PMID 35619118, 2022). "AREG has long been known as an oncogenic driver and promotes self-sufficiency in growth signals, tissue invasion and inhibition of apoptosis, all of which promote tumour progression." (PMID 35993275, 2022). "However, the activation of GPER1 hinders its anti-tumor capability by raising the intracellular Amphiregulin, IL6, IL8, antiapoptotic proteins, and invasivity promoting factors." (PMID 35337112, 2022). "High Amphiregulin, PTEN and low P21 expression levels were associated with low tumor grade (p= 0.038 and 0.025 respectively), better response to anti-EGFR treatment (p <0.001), and favorable outcome {progression-free survival (PFS) and overall survival (OS)} (p <0.05)." (PMID 33906293, 2021). "Amphiregulin is overexpressed in several epithelial neoplasms, including prostatic, colorectal, mammary, ovarian, pancreatic, pulmonary, hepatic, and oral neoplasms." (PMID 34468540, 2021).
tumor (continued). "In addition to acting on EGFR expressed on tumor cells, AREG has recently been shown to promote differentiation of T cells into TREGs within the tumor microenvironment." (PMID 34843542, 2021). "In view of the key role of AREG in tumor immunity, it is worthy of further exploration in EAC." (PMID 34724890, 2021). "Data obtained from mouse models revealed that amphiregulin (AREG) was produced by the tumor stroma of PC after damage (i.e., genotoxic chemotherapy and ionizing radiation), conferring resistance to immunosurveillance by increasing PD-L1 expression on cancer cells." (PMID 34830179, 2021). "We found that treatment with AREG antibody reduced the overall tumor burden (based on blood Gluc levels, p = 0.012); however, there was no significant reduction in the cell pellet volume of malignant ascites, suggesting that AREG antibody did not reduce the growth of CL31 tumor cells in the ascites." (PMID 33199705, 2020). "Among them, VEGF‐A and AREG were also present, confirming our results from the xenograft tumours." (PMID 31957261, 2020). "In TNBC, it has been suggested that AR activation alters the tumor microenvironment, hence suppressing the antitumor response and upregulating the secretion of the epidermal growth factor receptor (EGFR) ligand amphiregulin (AREG), both stimulating tumor growth and progression." (PMID 33138097, 2020). "In our in vivo model of xenografts, mouse fibroblasts could be further activated by celecoxib-induced secretion of EGF and AREG by epithelial tumor cells and by a stress environment characteristic of castration-resistant cells." (PMID 31816863, 2019). "Although IL13Rα2 expression in the SK-MEL-28 cells slightly upregulated the expression of vascular endothelial growth factor (VEGF), a well-known tumour angiogenic factor, the upregulation can be considered minimal (1.5-fold), compared to that of amphiregulin (3.2-fold)." (PMID 30718742, 2019). "Accordingly, reduced amphiregulin expression may decrease initiating events and, thereby, tumor incidence in MEPT by diminishing proliferation in the normal mammary epithelium." (PMID 31355130, 2019). "Both of DKK1 and AREG may play significant roles in tumor progression and may offer promising therapeutic targets in HCC patients." (PMID 31649806, 2019). "Serum AREG relation to metastasis suggests that tissue targeting of different AREG forms may represent a novel trend to prevent tumor progression and metastasis in HCC patients." (PMID 31649806, 2019). "Low expression levels of AREG and EREG associated with KRAS mutations might indicate a tumor that is less dependent on EGFR and is therefore particularly prone to developing resistance to anti-EGFR MoAbs." (PMID 31771279, 2019). "In summary, loss of AREG appears to enhance expansion of tumorigenic lesions and accelerate tumor progression, but does not have an effect on intravasation and metastasis." (PMID 30367629, 2018). "Together, these data suggest that GOF mutations in RHBDF2 accelerate tumor growth with an associated increase in AREG secretion, suggesting a critical role for RHBDF2 in controlling tumor growth through enhanced secretion of AREG." (PMID 30022999, 2018). "Based on these data, promoter DNA methylation may be the main regulatory mechanism of AREG/EREG expression, which may explain, at least in part, the association between right-sided tumor location, CIMP-status and anti-EGFR treatment response in mCRC." (PMID 34532592, 2018). "Our data indicate that AREG expression identifies a subset of PDAC patients with more aggressive tumor characteristics and a significantly worse prognosis, indicating that AREG may serve as an attractive therapeutic strategy for PDAC." (PMID 27391842, 2016).
tumor (continued). "Noteworthy, higher reduction of secreted chemokines having pro-tumorigenic/invasion effects was observed with anchored-bCet compared to bCet paralleled by an impressive increase of secreted Amphiregulin which is known to be a relevant predictive marker of tumor cell sensitivity to Cetuximab." (PMID 26575422, 2016). "These discrepancies may be a result of different cancer types, use of different cell lines, heterogeneous methods used to detect AREG expression, and/or differences in AREG concentrations in the local tumor microenvironment and the systemic circulation." (PMID 27004400, 2016). "Moreover, the concomitant expression of AREG and EGFR was associated with enhanced tumor aggressiveness and shorter survival periods following tumor resection in PDAC." (PMID 27391842, 2016). "Moreover, AREG expression, poor tumor differentiation, high TNM stage, and positive resection margins were all independent prognostic indicators for poor OS." (PMID 27391842, 2016). "Eight genes were downregulated after S6K1 silencing, but upregulated after S6K2 knock-down, among these the EGFR ligand amphiregulin (AREG), the glutamate-ammonia ligase (GLUL) involved in glutamine synthesis, and the CDK5 and ABL1 enzyme substrate 1 (CABLES1), implicated as a tumour suppressor." (PMID 26698305, 2015). "A second possibility is that amphiregulin might induce the recruitment and proliferation of stromal cells like endothelial cells and fibroblasts which promote tumor progression." (PMID 25884419, 2015). "The expression of AREG had significantly increased with tumor progression." (PMID 26503469, 2015). "AREG is one of essential miR-34a targets, over-expression of which could rescue miR-34a mediated tumor invasion defects and EGFR inhibition." (PMID 25762634, 2015). "The tumour specific and cytoplasmic expression of amphiregulin supports the notion of a switch in autocrine signalling and it has been reported that amphiregulin is a prognostic marker for poor outcome of a variety of malignancies including colorectal liver metastasis." (PMID 25872475, 2015). "The effect of AREG on tumor migration has been explained previously." (PMID 26503469, 2015). "Suppression of AREG by ectopic miR-34a expression prevented tumor invasion, and inhibited EGFR, which might be the potential molecular targets for future HNSCC therapy." (PMID 25762634, 2015). "Tumor cell specific targeting may be necessary and tumor and or tumor-host interaction generated secreted factors, such as AREG and/or VEGF may be used as follow-up factors to monitor treatment and diseases progression." (PMID 26299613, 2015). "Recent decade, studies have demonstrated AREG can indeed behave as a pro-oncogenic factor and highlighted the multiple functional roles of AREG over-expression in inhibition of apoptosis and promoting proliferation, motility, angiogenesis, and tumor invasion and metastasis in many solid tumors." (PMID 25762634, 2015). "In our series this was the case for AREG, however tumour EREG mRNA retained predictive significance for survival both in KRAS wild-type as well as mutated cases, a counter-intuitive finding, further supported by the predictive significance of EREG for response, even in KRAS mutant patients." (PMID 23374602, 2013). "It is thought that elevated expression of epiregulin and/or amphiregulin may stimulate an autocrine loop through EGFR thus promoting tumor growth and survival." (PMID 24212785, 2011). "In addition, previous reports have confirmed that TACE-mediated transactivation of EGF receptors by amphiregulin is important for tumor cell growth and migration." (PMID 21423656, 2011). "Importantly, strategies targeting AREG have shown not only antifibrotic effects but also anti-tumor potential, presenting a promising therapeutic approach that could simultaneously target fibrosis and cancer progression." (PMID 40725192, 2025). "However, there are limited studies evaluating AREG’s role in tumor immunology." (PMID 38831884, 2024).
tumor (continued). "The binding of lactate to this receptor could eventually lead to the activation of the phosphatidylinositol 3-kinase (Pi3K)/protein kinase B (Akt) pathway, resulting in the release of amphiregulin, which stimulates angiogenesis of tumor endothelial cells, tumor cell growth, and proliferation." (PMID 38731909, 2024). "Notably, AREG expressed by Treg cells has been shown to promote tumor growth." (PMID 37611111, 2023). "Moreover, AREG mAbs and IL-33 concertedly inhibited tumor growth." (PMID 37611111, 2023). "Similarly, for the measurements from 2018 that compared 39 CRC cases to 102 controls free of neoplasms, adjusted p-values ≤0.05 were observed for six protein biomarkers and AUCs ≥0.7 were observed for the same two biomarkers, AREG and CEA, in the second measurements." (PMID 35330110, 2022). "Evidence suggests that ADAM17 promotes tumor-associated macrophage polarization and angiotensin II-mediated pro-growth and pro-migration signals by shedding EGFR ligands, including heparin-binding EGF-like growth factor (HB-EGF) and AREG (members of the EGF family), from the cell membrane." (PMID 36466812, 2022). "Since multiple secreted factors identified above, including AREG, PAI-1, CCL2, CCL5, IL6, IL8, and CSF2, are also known to be regulated by yes associated protein (YAP), we investigated whether V2R regulates YAP in ccRCC tumor cells." (PMID 35886951, 2022). "AREG-EGFR signaling may be important in tumor proliferation and repair in the TME." (PMID 31681327, 2019). "We speculate that AREG-EGFR interactions in the TME facilitate tumor growth and invasion." (PMID 31681327, 2019). "However, an increase of AREG mRNA expression in tumour tissue was reported twice." (PMID 27933395, 2017). "Thus, AREG might serve as a master regulator and participate in the alteration of multiple cellular events related with tumor progression." (PMID 27713123, 2016). "We next tested whether silencing of AREG in fibroblasts affected tumor supportive function." (PMID 24068959, 2013). "Interestingly, secretion of amphiregulin by fibroblasts appeared to potentially act as a chemoattractant to recruit new fibroblasts and induce their proliferation and activation, resulting in a tumor microenvironment that is enriched in activated fibroblasts." (PMID 24068959, 2013). "AREG was not statistically significant as categorical variable but EREG mRNA at the 75th percentile was associated with a 2.26-fold increased likelihood of tumour response to cetuximab compared to tumours with lower EREG mRNA expression." (PMID 23374602, 2013). "Moreover, patients with tumours exhibiting higher EREG or AREG expression had significantly longer PFS, suggesting that these tumours were EGFR dependent and were therefore particularly sensitive to the inhibition of the ligand–receptor interaction by anti-EGFR mAb." (PMID 21139621, 2010). "Notable tumor-associated factors that appear to be highly expressed only in the Lewis lung cancer cell line that are also known to be involved in cancer, are osteopontin, kit ligand (stem cell factor), chemokine (CXC) ligand 1, pleiotropin, fibroblast growth factor 7, amphiregulin and epiregulin." (PMID 18489769, 2008). "Genes associated with MAPK signaling cascades, a major downstream pathway of EGFR signaling (AREG, JUN, DNAJB1, DUSP1), were upregulated in tumor C0 NK cells." (PMID 41082397, 2026). "TPST1-high tumor cells exhibited proliferative enrichment and potential interaction with myeloid cells via PTN-NCL and EREG/AREG-EGFR signaling pathways." (PMID 41838327, 2026). "Disruption of the amphiregulin-EGFR axis prevents early niche formation and abrogates tumour initiation." (PMID 42020743, 2026). "We investigated entinostat effects on EGFR and amphiregulin (AREG) expression in various cell line- and primary patient tumor-based in vitro, ex vivo and in vivo models, on the mRNA and protein level." (PMID 39864337, 2025).
tumor (continued). "Targeting AREG has emerged as a promising strategy to overcome EGFR inhibitor resistance and suppress tumor progression across various cancer types." (PMID 40725192, 2025). "Combinational therapeutic strategies that include AREG-targeted inhibitors can reprogram the TME, enhancing anti-tumor efficacy." (PMID 40725192, 2025). "In our investigation, we examined the expression of genes connected to stemness in the different tumor cell subtypes and determined that the expression levels of ATF3, CXCL2, RRAD, AREG, and CXCL8 were significantly higher in the C0 subtype." (PMID 40936936, 2025). "In contrast, the in vivo treatment of patient #1 PDX tumor-bearing mice confirmed the parallel ∼ 2.5-fold upregulation of EGFR and AREG." (PMID 39864337, 2025). "This invGRN comprises fDEGs and is activated by subtypes of EGFR-activity that are primarily governed by EGFR ligands AREG, EREG, and HBEGF in single tumor cells." (PMID 40121428, 2025). "Taken together, we demonstrated that the induction of AREG by E2 contributes to EGFR activation, which then affects cell proliferation and tumor growth." (PMID 40422206, 2025). "Most of the 313 new disease links belonged to the DisGeNET class neoplasms (n = 40; EGFR, ERBB2, KITLG, AREG) but also to immune diseases (n = 29; FAS), neurological diseases (n = 13; PNPLA6), and cardiovascular diseases (n = 13; CD163)." (PMID 40593564, 2025). "The protein product of AREG is a ligand for the EGF/TGF-α receptor with connection to EMT, increased tumor cell migration and proliferation, and has been reported as a prognostic biomarker for treatment targeting EGFR in other cancer entities." (PMID 40082664, 2025). "EGFR-activity subtypes characterized by accumulating expression of AREG and concurrently reduced expression of epithelial marker EpCAM promote de-differentiation towards EMT, local invasion, tumor budding, and are correlated to worsened OS." (PMID 40121428, 2025). "The bar graphs indicated that the expression profiles of ATF3, CXCL2, RRAD, AREG, and CXCL8 in the C0 subtype were expressed at greater levels than in the remaining tumor cell subtypes." (PMID 40936936, 2025). "Analysis of TCGA database (accession number: phs000178) revealed increased PSI values for ACTA2, AREG, BRCA1, DDX5, MSH6, and PARP1 in tumor tissues compared to adjacent tissues." (PMID 39773744, 2025). "Combined with the results of previous results in this paper, it can be concluded that the C1 SRSF7+ MCs and tumor cells crosstalk through the AREG-EGFR/AREG-(EGFR+ERBB2) signal pathway, thereby exerting a tumor-promoting effect." (PMID 39430754, 2024). "The suppressive function of Tregs is enhanced by ILC2s production of AREG protein, promoting EGFR-expressing tumor progression." (PMID 39309440, 2024). "For the AREG and ERBB3 signaling pathway, there was expression of AREG across all the cell types and datasets, supporting its role in signaling to ERBB3, which is expressed exclusively in the tumor epithelial cells." (PMID 38183074, 2024). "MAbs and ADCs targeting EREG and AREG are in preclinical development and have thus far demonstrated to be well-tolerated while achieving TGI in variety of tumor models, including CRC." (PMID 40727266, 2024). "In both the CD8 TIL-tumor coculture and the CD8 CEA-CAR coculture, increased levels of TNF were observed, as well as increased IL-6 and AREG levels in the anti-CEA-CAR system." (PMID 38226976, 2024). "In liver cancer, for example, amphiregulin, an EGFR ligand produced by tumor cells stabilizes Treg cell function, which potentially facilitates tumor growth and metastases." (PMID 37432606, 2023). "Thirteen cases were histologically reviewed, characterized for tumor‐infiltrating lymphocytes (TILs), and were subjected to immunohistochemistry for programmed death‐ligand 1 (PD‐L1, clone 22C3), EGFR, and amphiregulin (AREG)." (PMID 36916425, 2023).